ABCG2 (ATP binding cassette subfamily G member 2 (JR blood group))
Diseases named in the same sentence as ABCG2 in open-access papers (continued):
Sharing a sentence is not in itself a finding about the gene and the disease.
cancer (continued). "Interestingly, ABCG2 was also found to be a determinant of side population (SP) cells that are highly enriched in cancer stem cells." (PMID 26556876, 2015). "Therefore, it is likely that A-803467, in combination with anticancer agents that are ABCG2 substrates, would be very useful in the treatment of certain drug resistant cancers." (PMID 26515463, 2015). "The mechanism may be associated with the reduced expression of cancer stem cell markers HIF-2α, Oct-4 and ABCG2." (PMID 25452783, 2015). "Based on these findings, we investigated the variation of ABCG2 expression; the gene expression and the protein levels of this transporter were quantified in cancer and endothelial cell lines exposed to the different drugs at the experimental IC50 in hypoxic conditions." (PMID 26623560, 2015). "Fumitremorgin C, a highly specific ABCG2 inhibitor, is too neurotoxic for clinical use; despite their effectiveness in vitro, these inhibitors are scarcely suitable for clinical application for cancer treatment because of their intolerable toxicities." (PMID 26305906, 2015). "As we known, ABCG2 protein attached to ABC protein family was commonly expressed in carcinoma cell." (PMID 26149707, 2015). "We speculate that cancer stem-like cells may exist in the cells with ABCG2+++/Ki-67− staining, which are surrounded by cells expressing both ABCG2 and Ki-67 in ACC and ABCG2 may play a role in the process of cellular proliferation and development in ACC." (PMID 24804195, 2014). "To address this question in humans, in future research, we will investigate whether the percentage and number of tolerogenic DCs and Treg cells are altered in MDR cancer patients receiving treatment with ABCG2 inhibitor and anti-cancer drugs." (PMID 25111504, 2014). "We speculate that the cancer stem-like cells may exist with ABCG2+++/Ki-67− staining, which are surrounded by cells with positive expression of ABCG2 and Ki-67 in ACC." (PMID 24804195, 2014). "Understanding the relationship between COX-2 and ABCG2 may open novel perspectives in cancer therapy, in which, coxibs could be employed as a chemotherapy-supporting treatment." (PMID 25587329, 2014). "On the other hand, treatment of human cancers with histone deacetylase (HDAC) inhibitors may result in expression of ABCB1 or ABCG2 or both." (PMID 25268163, 2014). "We hypothesized that afatinib can effectively compete with chemotherapeutic agents for binding with ABCB1, ABCC1, or ABCG2 and thus increase drug concentrations in resistant cancer cells." (PMID 25436978, 2014). "The highest intensity of ABCG2 staining was mainly localized in the periphery of cancer nests." (PMID 24804195, 2014). "In contrast, in this study, we showed that afatinib could reverse the drug resistance and enhance the cytotoxicity of conventional anticancer drugs in ABCG2-overexpressing cancer cells by a dual inhibition of ABCG2." (PMID 25436978, 2014). "ABCG2 belongs to the ATP-binding cassette transporter superfamily that contributes to multiple drug resistance in cancers and permits cells in vitro to export the fluorescent dye Hoechst 33342, a technique used to define a side population of purported stem cells 13–16." (PMID 24415717, 2014). "Inhibition or down-regulation of ABCG2 may be a valid approach to reverse ABCG2-mediated drug resistance and to improve the clinical efficacy of cancer chemotherapy." (PMID 25436978, 2014). "Alteration in ABCG2 expression and activity can significantly affect the disposition of the transporter drug substrates, so it's over expression in cancer cells is responsible for decreasing in drug concentration within the cell and a reduced cancer-chemotherapy efficacy." (PMID 25587329, 2014). "Both normal and cancer stem cells express transmembrane transporters, including ABCG2." (PMID 25216750, 2014). "Breast cancer resistance protein (BCRP/ABCG2) is an ATP-binding cassette transporter, which may directly cause resistance of cancer cells by active efflux of anticancer drugs." (PMID 24338217, 2014).
cancer (continued). "The ABCG2 (G-subfamily of human ABC) transporter was downregulated in cancer cells." (PMID 25250324, 2014). "Taken together, our findings may provide a new and useful combinational therapeutic strategy of afatinib with chemotherapeutical drug for the patients with ABCG2 overexpressing cancer cells." (PMID 25436978, 2014). "Therefore, TKIs can be exploited to overcome resistance by increasing the intracellular concentration of P-gp and/or ABCG2 substrate anticancer drugs in cancer cells, tissues or tumors that express high levels of these transporters." (PMID 25436978, 2014). "Combination of telatinib with specific ABCG2 substrate drugs may be useful in treating human carcinomas especially those overexpress ABCG2 in clinic." (PMID 25268163, 2014). "ATP-binding cassette, subfamily G, member 2 (ABCG2) is widely expressed in both normal and cancer stem cells and may play an important role in cancer malignant behaviors." (PMID 24194752, 2013). "In the current study, we demonstrated that combined treatment with cisplatin and curcumin reduced the expression of ABCG2 in CD133+ cancer stem cells, indicating that curcumin may suppress ABCG2-induced chemoresistance in CD133+ HEp-2 cells." (PMID 24223665, 2013). "To confirm the stemness feature of ABCG2+ sorted cells, we performed a genome-wide study of cancer stem cell gene expression on these cells using a stem cell real-time PCR array (RT2 profiler PCR Array-Human Stem Cell signalling pathway; Qiagen Sciences, Philadelphia, PA, USA)." (PMID 23559012, 2013). "ABCG2 is a key human ATP-binding cassette (ABC) transporter mediating cancer cell chemoresistance." (PMID 24312054, 2013). "The ability of curcumin to enhance the effectiveness of cisplatin in HEp-2 cells and induce the sensitivity of CD133+ cancer stem cells to cisplatin by suppressing ATP-binding cassette sub-family G member 2 (ABCG2)-mediated chemoresistance in vitro was evaluated." (PMID 24223665, 2013). "A screening study identified two compounds as potential ABCG2-related CS agents in HEK293 transfected cells, one of them (NSC103054) directly interacting with the transporter, and very recently an ABCG2 inhibitor (NP-1250) was reported to induce CS in mitoxantrone-selected MCF7 cancer cells." (PMID 24312054, 2013). "The increased level of ABCG2 in BFTC cells overexpressing AR may explain their higher viability under anti-cancer drug treatment." (PMID 23599788, 2013). "Interestingly, in drug-selected MCF7 cancer cells, which also overexpress ABCG2, the intracellular glutathione content was significantly higher than in the parental MCF7 cells (154 ± 7 versus 125 ± 10 nmol glutathione/mg protein)." (PMID 24312054, 2013). "In addition, there was no inverse correlation between the observed decrease of intracellular GSH and increase of extracellular GSH, as also noticed in other drug-selected cancer cells overexpressing ABCG2." (PMID 24312054, 2013). "ABCG2 has been suggested to be a survival factor for stem or cancer stem cells (CSCs)." (PMID 24358977, 2013). "As an important multidrug resistance transporter, ABCG2 has the capability of efflux various chemotherapy drugs and may contribute to drug resistance of cancer cells." (PMID 24194752, 2013). "Furthermore, it was reported recently that ABCG2 was distributed in the mitochondrial fraction of multidrug resistant (MDR) cancer cell lines." (PMID 23189181, 2012). "Finally, the inhibition of Hh/Gli by CK2α siRNA led to a reduction of a cancer stem cell-like side population that shows higher ABCG2 expression level." (PMID 22768056, 2012). "Expression analysis of post-differentiation mixed-populations indicates reduced transcripts of the ABC-transporter and cancer stemness marker ABCG2 and higher expression of cell proliferation marker minichromosome maintenance 7 (MCM7) compared to undifferentiated SP-fractions." (PMID 22768203, 2012).
cancer (continued). "Some researchers reported the dye-effluxing side population cells expressing ABCG2, an ATP-binding cassette half-transporter, could be isolated as cancer stem cells." (PMID 22745705, 2012). "Application of this pegylated SN38 formulation may therefore be a useful clinical approach to bypass ABCG2-mediated resistance to conventional camptothecin analogues in cancers with defects in homology-directed DNA repair." (PMID 23028879, 2012). "ABCG2 is an ATP-binding cassette (ABC) efflux transporter, and its overexpression in cultured cells was found to cause resistance to various clinically used anti-cancer drugs, such as topotecan and irinotecan." (PMID 23028879, 2012). "In summary, CSC promotes chemoresistance via Akt-mediated regulation of ABCG2 activity, and may also increase the proportion of cancer stem-like cells, contributing to tumor resilience." (PMID 23144836, 2012). "Thus, MDR modalities including ABCG2-dependent drug sequestration within EVs can be rationally converted to a pharmacologically lethal Trojan horse to selectively eradicate MDR cancer cells." (PMID 22530032, 2012). "On the contrary, inhibition of ABCG2 resulted in an impaired migration and tube formation of human microvascular endothelial cells and also in inhibition of cellular proliferation in cancer cell lines." (PMID 22952907, 2012). "One possible explanation could be that the different environmental factors or different sample size of the two studies may influence the function of the ABCG2 C421A for developing cancer." (PMID 22937733, 2012). "Its overexpression has been demonstrated that endogenous ABCG2 expression in certain cancers is possibly a reflection of differentiated phenotype of cell origin and may contribute to intrinsic drug resistance in vitro." (PMID 21943250, 2011). "In conclusion, artesunate is an effective anti-cancer drug that may enhance the effectiveness of other anticancer drugs and may reverse multi-drug resistance by suppressing the transcription of ABCG2, which inhibits drug efflux." (PMID 22183882, 2011). "However, targeted therapy with ABCG2 antagonist can only inhibit partially the growth of SP cells and cancer stem cells." (PMID 21542915, 2011). "Our results also indicate that co-targeting BCRP/ABCG2 may not only overcome gefitinib resistance but also broaden the clinical use of gefitinib for various cancers with wtEGFR." (PMID 21731744, 2011). "The induced BCRP/ABCG2 caused an efflux of gefitinib from the resistant but not sensitive A431 cancer cells." (PMID 21731744, 2011). "Overexpression of Bmi-1, ABCG2 and cyclin D1 and downregulation of p16 could contribute to these phenotypic changes of Panc-1 cancer stem cells." (PMID 21673909, 2011). "ABCG2 is a member of this family and represents a purified marker of cancer stem cells." (PMID 21542915, 2011). "As hormone influence plays an important role in prostate cytodifferentiation, lack of androgen may also lead to increased expression of progenitor cell markers (CD133, CD44, CD117, ABCG2) in cancer cells." (PMID 21605402, 2011). "In this study, we employed wtEGFR-expressing and gefitinib-sensitive A431 epidermoid cell line and its gefitinib-resistant derivative, A431/GR to address whether BCRP/ABCG2 plays a role in determining EGFR-TKI sensitivity in wtEGFR-expressing cancer cells." (PMID 21731744, 2011). "Therefore, ABCG2/BCRP1 expression is a useful marker for positive selection of several types of cancer stem-like cells." (PMID 20354527, 2010). "The CSC-like phenotype of cancer SP cells might not only be determined by ABCG2, but also by GADD45β." (PMID 21048853, 2010). "Thus, ABCG2 is an interesting and promising target for development of chemo-sensitizing agents for better treatment of drug resistant cancers and for eliminating cancer stem cells." (PMID 21151870, 2010).
cancer (continued). "Overexpression of the three major ABC transporters, i.e. P-glycoprotein (Pgp), multidrug-resistance-associated protein 1 (MRP1) and breast cancer resistance protein (BCRP/ABCG2) is frequently observed in cancer cell lines selected with chemotherapeutic drugs and critical to clinical drug resistance." (PMID 20653978, 2010). "Accumulating evidence indicates that ATP-binding cassette (ABC) transporter ABCG2 plays a key role in regulating the cellular accumulation of porphyrin derivatives in cancer cells and thereby affects the efficacy of photodynamic therapy and photodynamic diagnosis." (PMID 21188243, 2010). "Moreover, constitutive activation of the hedgehog (HH) pathway induces chemoresistance in a variety of cancers including PDAC by regulation of ABC transporter expression, like ABCB1 and ABCG2." (PMID 24212609, 2010). "In fact, high expression of ABCG2 has been found in a wide variety of cancer stem cells." (PMID 19390592, 2009). "Thus, ABCG2 is an ideal target for development of chemo-sensitizing agents for better treatment of drug resistant cancers and helping eradicate cancer stem cells." (PMID 19479068, 2009). "MDR cancer cells overexpressing ABCC1 or ABCG2 and their sensitive parental cell lines were used." (PMID 19390592, 2009). "ABCG2 is found to be expressed in a wide variety of cancer stem cells and may be responsible for their drug resistance phenotype." (PMID 19390592, 2009). "Nevertheless, the observations from this study clearly indicate that PZ-39 may serve as a lead compound for further design and optimization of more specific ABCG2 inhibitors for better treatment of drug resistant human cancers in combinational therapy." (PMID 19479068, 2009). "Moreover, the selection of IGROV-1 and S-1 cancer cells with 14 or 21 nM doxorubicin also resulted in the overexpression of ABCG2." (PMID 18382425, 2008). "Therefore, investigating how tinodasertib interacts with ABCG2 and whether it can overcome drug resistance could greatly enhance its clinical utility, especially in cancers where resistance to standard treatments poses a significant challenge." (PMID 40584625, 2025). "Likewise, Abcg2-encoding BCRP and Abcb1-encoding ABCB1 are critical transporters at the BBB that restrict the brain permeability to its physiological substrates and anti-cancer drugs in vivo." (PMID 39578077, 2025). "Functioning primarilly as a defensive transporting pump, ABC sub-family G member 2 (ABCG2) can uptake its cellular substrates, including many cytotoxic agents such as anticancer drugs that are structure different, and then move them out of cancer cells, leading to acquired drug resistance." (PMID 40066335, 2025). "One of the primary mechanisms by which cancer cells acquire multidrug resistance is through the overexpression of ATP-binding cassette (ABC) transporters, such as P-glycoprotein (P-gp/ABCB1), multidrug resistance-associated proteins (MRPs), and breast cancer resistance protein (BCRP/ABCG2)." (PMID 40843170, 2025). "However, the mechanisms by which the ABCG2 gene becomes underexpressed in cancers remain unknown, as well as relatively little being known about the mechanisms that physiologically regulate the expression of this gene." (PMID 39457707, 2024). "Moreover, other multidrug resistant cancer cells such as BCRP-overexpressing S1-MI-80 cells, HEK293/ABCG2-482-R2 cells and HEK293/ABCG2-482-T7 cells, MRP1-overexpressing HL60/adr cells and their corresponding parental cells were also confirmed and used in the following experiments." (PMID 38872211, 2024). "Thus, ABCG2-dependent augmentation of glutamine uptake and glutaminolysis could enhance survival of cancer cells subject to metabolic stress." (PMID 38641063, 2024). "However, the recent explosion of anti-cancer target drugs, often substrates of ABCG2, has led to the identification of several compounds with high ABCG2 affinity and strong efflux inhibition ability that may be “repurposed” as ABCG2 reversal agents." (PMID 38255216, 2024).
cancer (continued). "In addition, the fibroblasts expressed low levels of drug resistance genes, like ABCG2, that could make them appear more sensitive to some drugs than cancer cell lines, as in the analysis of HT-29 heterospheroids." (PMID 39011470, 2024). "Thus, regulating PTEN using some appropriate modulators could be used as a novel approach to inhibit PI3K/AKT mediated ABCG2 overexpression in drug-resistant cancer cells." (PMID 37919637, 2023). "The role of ABCG2 in colorectal cancerogenesis could be linked with the transport function of the protein, but it could also indicate its participation some signalling pathways or protein interactors, which may determine the role of ABCG2 in cancer cell self-renewal and behaviour." (PMID 37445716, 2023). "Furthermore, the efficacy of HS-173 could be recovered through inhibiting the drug-efflux function of ABCB1 and ABCG2 in multidrug-resistant cancer cells." (PMID 37048130, 2023). "Based on our in vitro results, in particular the ability of non-toxic carborane-based ABCG2 inhibitors to affect ABC transporter-associated doxorubicin and cisplatin efflux, thus sensitizing the examined cancer cells for the applied therapeutics, future in vivo studies are of interest." (PMID 38004447, 2023). "In addition, several studies have shown that the PI3K/AKT pathway enhances the biological basis of cancer through ABCG2, and its activation may reduce the response to chemotherapy drugs and enhance drug efflux." (PMID 37919637, 2023). "As the overexpression of ABCB1 and ABCG2 is known to be a common mechanism responsible for the development of drug resistance in cancer cells, the purpose of this study is to determine whether HS-173 is susceptible to efflux in human cancer cells induced by ABCB1 and ABCG2." (PMID 37048130, 2023). "ABCG2 is a medically important ATP-binding cassette transporter with crucial roles in the absorption and distribution of chemically-diverse toxins and drugs, reducing the cellular accumulation of chemotherapeutic drugs to facilitate multidrug resistance in cancer." (PMID 37596258, 2023). "Additionally, ABCG2 is also considered a marker of cancer stem cells (CSCs), a subpopulation of tumour cells with stem cell characteristics; these are believed to be responsible for cancer growth, drug resistance and recurrence." (PMID 37445716, 2023). "Furthermore, we found that the effect of HS-173 on G2/M cell-cycle arrest and apoptosis was substantially reduced in ABCB1-overexpressing KB-V1 and ABCG2-overexpressing S1-MI-80 cancer cell lines when compared to what was observed with their respective parental cell lines." (PMID 37048130, 2023). "Knowing that ABCB1 and ABCG2 could reduce the cytotoxicity of HS-173 in cancer cell lines, we next examined the impact of ABCB1 and ABCG2 on G2/M cell cycle arrest and apoptosis induced by HS-173, which are characteristic effects of HS-173 treatment in human cancer cell lines." (PMID 37048130, 2023). "We demonstrated that the drug transport activity of ABCB1 and ABCG2 could extensively lower the intracellular accumulation of HS-173 and consequently reduce its ability to induce G2/M phase cell cycle arrest and apoptosis in human cancer cells." (PMID 37048130, 2023). "Hence, it appears that ABCG2 expression level could depend on the cancer type and specificity of tissue origin, and its changes can reflect its role in the carcinogenesis process." (PMID 37445716, 2023). "Similarly, ABCG2 is also a major mediator of MDR in cancer cells." (PMID 35350768, 2022). "Furthermore, based on the normalized enrichment scores, we used gene set enrichment analysis (GSEA) that included related genes in humans to find general enrichment trends and to identify GO functional enrichment of different expression levels of ABCG2 among pan-cancer." (PMID 36555598, 2022).